EZH2 (enhancer of zeste 2 polycomb repressive complex 2 subunit)
Diseases named in the same sentence as EZH2 in open-access papers (continued):
Sharing a sentence is not in itself a finding about the gene and the disease.
psoriasis (8 papers, 2020 to 2026). An autoimmune condition characterized by red, well-delineated plaques with silvery scales that are usually on the extensor surfaces and scalp. "Future studies will be required to clarify whether EZH2 downregulation is causative in psoriasis pathogenesis or represents an adaptive response to the inflammatory milieu." (PMID 41518566, 2026). "Peripheral blood samples were obtained from 40 psoriasis patients and 18 healthy controls, and EZH2 expression in T cell and monocyte subsets was analysed by flow cytometry." (PMID 41518566, 2026). "This study observed decreased EZH2 expression in monocytes from psoriasis patients, suggesting a potential dysregulation in monocyte‐to‐macrophage differentiation and polarisation." (PMID 41518566, 2026). "This study aimed to evaluate EZH2 expression in peripheral blood mononuclear cells from patients with psoriasis and explore its potential functional relevance to disease pathogenesis." (PMID 41518566, 2026). "Future studies should explore the mechanistic links between EZH2 expression, immune cell dysfunction and chronic inflammation to better understand its potential as a therapeutic target in psoriasis." (PMID 41518566, 2026). "This study aimed to evaluate the expression of EZH2 across immune cell subsets in the peripheral blood of patients with psoriasis." (PMID 41518566, 2026). "Across all monocyte subsets, EZH2 expression levels were significantly lower in psoriasis patients than in healthy controls." (PMID 41518566, 2026). "This study aimed to elucidate the expression patterns of EZH2 in peripheral blood mononuclear cells (PBMCs) from psoriasis patients, with a focus on CD4+ T cells, CD8+ T cells and monocytes." (PMID 41518566, 2026). "Future comprehensive analyses incorporating other epigenetic modifiers and comparing tissue‐specific versus circulating immune cell populations will be critical to fully understand EZH2's role and its complex epigenetic regulation in psoriasis pathogenesis." (PMID 41518566, 2026). "Enhancer homolog 2 of the Zeste gene (EZH2) is a histone H3K27 methylase, whereas EZH2 acts on kallikrein-8 (KLK8) to cause the abnormal proliferation of keratinocytes in psoriasis." (PMID 37762693, 2023). "EZH2 inhibition effectively attenuates psoriasis-like skin lesions by suppressing STAT3-mediated IκBζ expression." (PMID 35795677, 2022). "Expression of EZH2 and H3K27me3 were compared in samples from six psoriasis lesional skin and six healthy controls by Real-Time PCR, western blotting and immunofluorescence staining." (PMID 33011750, 2020). "In our research, we focused on the role of EZH2 in catalyzing H3K27me3 in keratinocytes of psoriasis." (PMID 33011750, 2020). "Results from immunohistochemical staining showed that the expression of KLK8 was increased greatly in epidermis of psoriasis lesional skin, which is consistent with the change of EZH2." (PMID 33011750, 2020). "To study the effect of using EZH2 as a target for the treatment of psoriasis, we adopted GSK126, a small molecule chemical inhibitor of EZH2 to treat imiquimod-induced psoriasis-like mouse model." (PMID 33011750, 2020). "In vitro, the expression of EZH2 and H3K27me3 was stimulated in human keratinocytes treated with mixture of psoriasis-related cytokines pool (TNF-α, IFN-γ, IL-17A, and IL-22)." (PMID 33011750, 2020). "EZH2 is a potential molecular target for the treatment of psoriasis and are worth attention in the future drug discovery for psoriasis." (PMID 33011750, 2020). "Results from immunofluorescence showed that the expression of EZH2 in HaCaT cells was significantly upregulated after treatment with psoriasis-related mixed cytokines for 24 h." (PMID 33011750, 2020). "Despite the well‐established roles of T cells and monocyte‐derived cells in psoriasis, the role of EZH2 in these immune subsets remains unknown." (PMID 41518566, 2026).
psoriasis (continued). "Considering the significance of EZH2 in other autoimmune and inflammatory diseases, investigating its expression in immune subsets of psoriasis patients may uncover commonalities and differences with other immune‐mediated diseases." (PMID 41518566, 2026). "However, the precise role of EZH2 in monocyte‐mediated inflammation in psoriasis warrants further investigation." (PMID 41518566, 2026). "Collectively, these findings suggest that EZH2 may be involved in the regulation of type 3 inflammatory responses and may therefore represent an epigenetic regulator contributing to psoriasis pathogenesis." (PMID 41518566, 2026). "Enhancer of Zeste Homologue 2 (EZH2) is an epigenetic regulator involved in immune cell differentiation and function; however, its role in psoriasis remains unknown." (PMID 41518566, 2026). "In conclusion, our findings suggest that EZH2 downregulation may play a role in psoriasis pathogenesis, particularly through its effects on the function and differentiation of CD8 T cells and monocytes." (PMID 41518566, 2026). "EZH2 was previously shown to relate to keratinocyte proliferation and inflammatory responses in psoriasis, and it may also affect CD4+ and CD8+ T cell differentiation and epidermal stratification, potentially contributing to psoriatic hyperkeratosis." (PMID 40650108, 2025). "Our research provides a theoretical basis for the treatment of psoriasis by targeting EZH2." (PMID 33011750, 2020). "Our results showed that EZH2 could promote KC proliferation in the inflammatory environment of psoriasis in vitro." (PMID 33011750, 2020). "Considering that psoriasis is an inflammatory skin disease characterized also by epidermal hyperproliferation, it is hypothesized that EZH2 might affect the keratinocyte proliferation in psoriasis through epigenetic modification." (PMID 33011750, 2020). "Furthermore, we evaluated whether EZH2 expression correlates with disease severity to assess its potential as a biomarker in psoriasis." (PMID 41518566, 2026). "Furthermore, psoriasis patients exhibited a reduction in EZH2 expression in both naïve and memory CD8 T cells, suggesting that epigenetic dysregulation may occur early in T cell differentiation." (PMID 41518566, 2026). "This study uncovers the role of EZH2-dependent epigenetic modification in the regulation of psoriatic keratinocyte hyperproliferation and clarifies the related mechanisms, providing new evidence for the involvement of histone methylation in the pathogenesis of psoriasis." (PMID 33011750, 2020). "Furthermore, in HaCaT cells and psoriatic HaCaT cells which is stimulated with psoriasis-related mixed cytokines, knockdown of EZH2 could significantly reduce the expression of H3K27me3." (PMID 33011750, 2020). "A significant inverse correlation was observed between EZH2 MFI values in CD8+ naïve T cells and the Psoriasis Area and Severity Index (PASI) score." (PMID 41518566, 2026). "EZH2 expression was significantly reduced in circulating CD8+ naïve and memory T cells, as well as in monocyte subsets from psoriasis patients compared to healthy controls." (PMID 41518566, 2026). "EZH2 methylates and enhances STAT3 phosphorylation in keratinocytes and promotes inflammation in the psoriasis model." (PMID 35795677, 2022). "In this report, we showed that EZH2 promoted the proliferation of keratinocyte through KLK8, and inhibition of EZH2 had a therapeutic effect on psoriasis in imiquimod-induced psoriasis-like mouse model." (PMID 33011750, 2020). "Notably, a significant reduction in EZH2 expression, specifically in CD8+ naïve and memory T cells of psoriasis patients, was observed compared to healthy controls." (PMID 41518566, 2026). "In conclusion, our study showed upregulated EZH2 in psoriatic epidermis, which might catalyze trimethylation of H3K27, inducing the expression of KLK8 and further promotes keratinocyte proliferation in psoriasis." (PMID 33011750, 2020).
psoriasis (continued). "CCK8 analysis and EdU assays showed that the proliferation of HaCaT cells was significantly reduced after knockdown of EZH2, regardless of whether these cells are stimulated with psoriasis-related mixed cytokines." (PMID 33011750, 2020). "Analysis of all samples, including both psoriasis patients and healthy controls, revealed significantly higher EZH2 expression in memory CD4+ or CD8+ T cells compared to their naïve counterparts, suggesting a potential role of EZH2 in T cell differentiation, independent of disease status." (PMID 41518566, 2026).
T-cell leukemia (8 papers, 2014 to 2024). A malignant disease of the T-lymphocytes in the bone marrow, thymus, and/or blood. "Loss-of-function (LOF) mutations of EZH2 can lead to the development of T-cell leukemia, suggesting that it can also function as a TSG in malignant lymphoid cells." (PMID 34968237, 2020). "Decreased expression levels or loss-of-function mutations of EZH2 have similar effects and play a role in T-cell leukemia." (PMID 31143370, 2019). "It is also possible that this oncogenic action of EZH2 loss observed in T-cell leukemia may also be explained by the default function of EZH1 which replaces the role of EZH2 with a LOF mutation." (PMID 34968237, 2020). "EZH2 was found to be overexpressed in a variety of tumor entities and is thought to be involved in cancer progression of T-cell leukemia." (PMID 37297005, 2023). "However, malignancies with unmutated but overexpressed EZH2, such as T-cell leukemia, could also be suitable for EZH2 inhibition." (PMID 37297005, 2023). "To test this hypothesis, we first exposed Jurkat cells, a T-cell leukemia line, to the p38 MAP kinase inhibitor (10 nM) (Catalog number 506126, Calbiochem Co., La Jolla, CA, USA), which resulted in a decrease in the level of p-p38 and a significant increase in the level of Ezh2." (PMID 28740493, 2017).
acute promyelocytic leukemia (7 papers, 2011 to 2025). An aggressive form of acute myeloid leukemia (AML), characterized by arrest of leukocyte differentiation at the promyelocyte stage, due to a specific chromosomal translocation t(15;17) in myeloid cells. "Another example of the oncogenic function of EZH2 has been investigated in acute promyelocytic leukemia (APL)." (PMID 21795762, 2011). "In a separate study, using the EZH2 PROTAC-degrader MS1973, EZH2 degradation was necessary and more effective than enzymatic inhibition in eliminating relapse-initiating cells in a retinoic acid-dependent model of acute promyelocytic leukemia." (PMID 37664059, 2023). "From the perspective of RARα-mediated myeloid differentiation, EZH2 has been shown to play a role in a rare subtype of AML, acute promyelocytic leukemia (APL), which is generally curable with ATRA-based differentiation therapy (in contrast to non-APL AML)." (PMID 37035245, 2023). "For example, in acute promyelocytic leukemia (APL), disrupting the PRC2/EZH2 complex can not only reverse histone modifications but also induce DNA demethylation of PML-RARα target genes, which, in turn, reactivates differentiation-related genes and promotes cell differentiation." (PMID 39655332, 2024).
adenoid cystic carcinoma (7 papers, 2015 to 2024). A malignant tumor arising from the epithelial cells. "The aim of this study was to evaluate the expression of the EZH2 protein and describe the clinical and microscopic characteristics of adenoid cystic carcinoma (ACC) and pleomorphic adenoma (PA)." (PMID 38477804, 2024). "LncRNA MRPL23 antisense RNA1 (MRPL23-AS1) stimulated EMT by enhancing the activity of the enhancer of the zeste homolog 2 (EZH2) protein and its binding on the E-cadherin promoter region in adenoid cystic carcinoma (ACC)." (PMID 39682098, 2024). "In salivary gland tumors, although the amount of data is very limited, adenoid cystic carcinoma with a high EZH2 expression showed a high Ki-67 LI." (PMID 35186711, 2021). "LncRNA MRPL23-AS1 promoted adenoid cystic carcinoma lung metastasis by forming an RNA-protein complex with enhancer of zeste homolog 2 (EZH2) and increasing the binding of EZH2 and H3K27me3 on the E-cadherin promoter region." (PMID 33221763, 2020). "High expression of EZH2 detected by immunohistochemistry has been reported to predict poor survival for patients with adenoid cystic carcinoma." (PMID 26377323, 2015). "All the studied adenoid cystic carcinomas (n = 13) stained positively with EZH2 antibody." (PMID 26377323, 2015).
chronic kidney disease (7 papers, 2022 to 2025). Impairment of the renal function secondary to chronic kidney damage persisting for three or more months. "In summary, these findings highlight EZH2 as a potential therapeutic target for acute and chronic kidney diseases." (PMID 40833473, 2025). "Targeting EZH2 is expected to be a novel therapeutic approach for end-stage renal disease (ESRD) patients with PD treatment." (PMID 36619221, 2023). "However, according to previous studies, the long-term activation of this pathway may be related to the progression of AKI to chronic kidney disease, and whether EZH2 is involved in this process needs further investigation." (PMID 37064878, 2023).
chronic myelomonocytic leukemia (7 papers, 2012 to 2025). A myelodysplastic/myeloproliferative neoplasm which is characterized by persistent monocytosis, absence of a Philadelphia chromosome and BCR/ABL fusion gene, fewer than 20 percent blasts in the bone marrow and blood, myelodysplasia, and absence of PDGFRA or PDGFRB rearrangement. "Chronic myelomonocytic leukemia (CMML) has recently been associated with a high incidence of diverse mutations in genes such as TET2 or EZH2 that are implicated in epigenetic mechanisms." (PMID 22328940, 2012). "EZH2, the enzymatic component of PRC2 is mutated in myeloid malignancies, most commonly in MDS, chronic myelomonocytic leukemia (CMML), and primary myelofibrosis and rarely in AML." (PMID 29527516, 2018). "We also searched for TET2, DNMT3A, ASXL1, EZH2, IDH1/2 and CBL gene families mutations, given their potential clinical importance in diseases closely associated with SM like primary myelofibrosis, chronic myelomonocytic leukemia (CMML) and others." (PMID 22905207, 2012).
COVID-19 (7 papers, 2021 to 2024). A disease caused by infection with severe acute respiratory syndrome coronavirus 2. "Expression of EZH2 and MKI67 in adults with COVID-19 (particularly severe) and children with dengue (particularly secondary) indicated the presence of proliferative, “pre-plasmablast” cells in the peripheral circulation of these groups." (PMID 37638019, 2023). "The results showed that the interaction relationship between EZH2 and PTTG1 was the strongest in the COVID-19 dataset, and the expression was positively correlated." (PMID 37335738, 2023). "GFI1, ZNF90, E2F8, E2F2, and EZH2 were also specific to exhausted T cells and may play a vital role in TEX in severe COVID-19." (PMID 35694714, 2022).
depression (7 papers, 2022 to 2025). "Consistently, the inhibition of EZH2 was associated with improved cognitive function and relieved depression-like behaviors." (PMID 35172677, 2022). "Folic acid, a medication used for pregnancy, promoted astrocytic IL-10 expression by inhibiting EZH2-mediated H3K27me3 and improved depression-like behaviors in adult mice." (PMID 40108901, 2025). "EZH2 depletion contributes to suppressed inflammatory response and depression-like behaviors in obese depression mice." (PMID 35172677, 2022). "EZH2 expression was determined and then silenced to assess its effect on depression-like behaviors and neuroinflammation." (PMID 35172677, 2022). "EZH2 mediates neuroinflammation and depression-like behaviours, which is in line with the findings of the present study." (PMID 35230663, 2022). "EZH2 is highly expressed in depression rats, but its effect and mechanism in depression rats are yet to be elucidated." (PMID 35172677, 2022). "In a depression model induced by chronic unpredictable stress, EZH2 inhibitors improved depressive-like behaviors." (PMID 35197855, 2022). "In the present study, we revealed the expression of two downstream genes, NRF2 and SOCS3, was inhibited by the GAS5/EZH2 axis in the depression model." (PMID 35230663, 2022). "Our research focuses on the role and mechanism of EZH2 in depression, which provides a new direction for the treatment of depression." (PMID 35172677, 2022). "We verified the protective effect of silencing EZH2 on depression rats through in vivo and in vitro models, and found that EZH2 played an important role in regulating microglia polarization." (PMID 35172677, 2022). "Altogether, EZH2 silencing palliated neuroinflammation in depression rats by eliciting microglia M2-type polarization." (PMID 35172677, 2022). "The main purpose of this paper is to explore the effect and mechanism of histone methyltransferase EZH2 on neuroinflammation in depression rats." (PMID 35172677, 2022). "Our study pointed out the effect of EZH2 in neuroinflammation and microglia activation of depression with the participation of the miR-29b-3p/MMP2 axis." (PMID 35172677, 2022). "This experiment is designed to explore the role of EZH2 in inflammation of depression rats via microglia polarization, thus offering a therapeutic strategy for depression." (PMID 35172677, 2022). "Additionally, we performed a correlation analysis between EZH2 levels and depressive behaviors as well as neuronal apoptosis in mice and found that EZH2 expression was positively correlated with both the severity of depression and the extent of apoptosis." (PMID 41041075, 2025). "In summary, these findings suggest that EZH2 may serve as a key target in the pathogenesis of depression and is regulated by gut microbiota." (PMID 41041075, 2025). "We have demonstrated that EZH2 plays a critical role in gut-brain axis-related depression." (PMID 41041075, 2025). "However, the effects of EZH2 are not limited to neurodegeneration, but also extend to other neurological conditions such as depression, as demonstrated by studies on depression-like experimental models." (PMID 40723311, 2025). "Briefly, EZH2 silencing helps depression rats to recover from the depression-like behaviors." (PMID 35172677, 2022). "EZH2 silencing mitigated inflammation in depression by manipulating microglia M2-type polarization." (PMID 35172677, 2022). "This experiment was designed to investigate the mechanism of EZH2 on depression." (PMID 35172677, 2022). "Besides, miR-29b-3p was weakly expressed in depression rats and in LPS-induced cells, but increased upon EZH2 silencing." (PMID 35172677, 2022). "Altogether, EZH2 silencing helps to recover from the depression-like behaviors in depression rats." (PMID 35172677, 2022). "EZH2 catalyzes inflammatory infiltration and microglial activation in depression development." (PMID 35172677, 2022).
depression (continued). "Collectively, we made a hypothesis that EZH2 may influence neuroinflammation and microglia activation in depression via the regulation of miR-29b-3p/MMP2 axis." (PMID 35172677, 2022). "Thence, EZH2 might be involved in depression via modulating microglia polarization." (PMID 35172677, 2022). "However, the functional role of EZH2 in depression should be further investigated in future work." (PMID 35230663, 2022). "Interestingly, the inhibition of EZH2 in a depression model elevated the expression of SOCS3, which suggested that SOCS3 might regulate microglial activation in depression." (PMID 35230663, 2022). "In our experiments, depression rat model was established via the CUMS treatment, after which we observed that EZH2 was robustly expressed in depression." (PMID 35172677, 2022). "It was documented in a recent report that in depression rat challenged by CUMS, EZH2 expression was promoted." (PMID 35172677, 2022). "In conclusion, our data supported that EZH2 targeted miR-29b-3p expression by promoting H3K27me3 level to elevate MMP2 transcription and trigger microglia M1-type polarization, so as to exacerbate depression-like behaviors and neuroinflammation in depression rats." (PMID 35172677, 2022).